CCR7 (C-C motif chemokine receptor 7)
Diseases named in the same sentence as CCR7 in open-access papers (continued):
Sharing a sentence is not in itself a finding about the gene and the disease.
infection (continued). "Together, these studies during infection demonstrate that the functions of CCR7 are largely redundant for cytotoxic T cell responses but indicate that they are critical for Th1 responses against intracellular parasites." (PMID 24205367, 2013). "At day 14 after infection, the percentage of CD11c+ cells expressing CCR7 in B6.WT mice was 74.3% (±2.5 [SEM]) in the footpad, 25.1% (±2.1) in the lymph node and 43.3% (±2.2) in the spleen." (PMID 24205367, 2013). "The proportion of CD4+IFN-γ+ T cells was increased significantly in B6.CCR7-/- mice as compared to B6.WT mice at day 14 after infection." (PMID 24205367, 2013). "Throughout the infection there was an increased proportion of CD4+ cells expressing Foxp3 in B6.CCR7-/- mice." (PMID 24205367, 2013). "Similar to our L. major model, CCR7-/- mice infected with T. gondii show a reduced migration of CCR2+ inflammatory monocytes to the site of infection." (PMID 24205367, 2013). "Our data further demonstrates that the role of CCR7 is extremely complex in infection models, and more studies are required to further elucidate the mechanisms of action between CCR7 and its ligands." (PMID 24205367, 2013). "While there have been many studies on the function of CCR7 during homeostasis or using model antigens, there are very few studies on the role of CCR7 during infection." (PMID 24205367, 2013). "Overall, there is an early increase in the macrophage-activating Th1 cytokines IFN-γ and IL-12, followed by an increase in Th2 and immunosuppressive cytokines from the peak of disease into the chronic stage of infection in B6.CCR7-/- mice." (PMID 24205367, 2013). "After subcutaneous infection with L. major, B6.CCR7-/- mice were unable to resolve the lesion and developed a chronic infection." (PMID 24205367, 2013). "At day 28 post infection there was an increase in IL-10-producing cells in B6.CCR7-/- mice, which was also seen in CD8+ cells." (PMID 24205367, 2013). "We also found an increased percentage of regulatory T cells in the draining lymph node of B6.CCR7-/- mice throughout infection." (PMID 24205367, 2013). "In the infection of B6.WT and B6.CCR7-/- mice presented, we saw a two-phasic footpad swelling (peaks at day 21 and day 105) in the clinically healthy control group." (PMID 24205367, 2013). "In our experiments, infection of B6.CCR7-/- mice with L. major, which is also eliminated by a protective Th1 response, does not result in death, but the mice are still unable to clear the parasite, and suffer from a chronic infection." (PMID 24205367, 2013). "Infection in the periphery leads to the development of a stable, antigen-independent CCR7+ central memory T-cell population with the potential to modulate the quality of T-cell responses after secondary antigen encounter." (PMID 22533989, 2012). "Altogether, we conclude that upon T. gondii-infection, DC exhibit a relative up-regulation of CCR7 that is consistent with the observed chemotactic responses in vitro." (PMID 23236276, 2012). "Flagellin427–441-specific T cells started to contract as early as day 10 following infection, and this coincided with a gradual increase in the percentage of cells expressing CCR7 and CD27." (PMID 22275869, 2012). "Some other genes such as CCL21, CXCR4, CCR1 and CCR7 exhibited a gradual increase during the infection." (PMID 22905138, 2012). "Migration of DCs after MV infection is further supported by a strong induction of lymph node homing chemokine CCR7." (PMID 23227146, 2012). "In models of infection-induced inflammation, CCR7 and its ligands have been clearly shown to play a protective role." (PMID 22533989, 2012). "Since CCR7 was expressed at high levels on brain DCs, the expression of the chemokine CCL21 (ligand for CCR7) was elevated during infection, and CCR7 on the brain DCs was functional in in vitro chemotaxis studies, this receptor was first targeted." (PMID 21949652, 2011).
infection (continued). "The lack of mDC accumulation in lymph nodes despite evidence for enhanced CCR7/CCL19-mediated recruitment in progressive infection led us to suspect that lymph node mDC were dying at an increased rate in these tissues." (PMID 21203477, 2010). "First, years after infection high numbers of these CCR7− Gn465–473–specific cells remain available for immuno-vigilance in the periphery." (PMID 20174562, 2010). "Comparing the mock and SARS-CoV infected adult DCs, there was moderate induction of CCR-1, CCR-3, CCR-5 and CCR-7 at both 3 h and 9 h post infection but only that observed for CCR-1 and CCR-5 reached statistical significance." (PMID 19505311, 2009). "While this activity and the regulation of Th17 cells may generally be considered beneficial during infection, the expression of ccr7 and ccl22 may suggest otherwise." (PMID 40682363, 2025). "Although there appeared to be overall immunosuppressive changes to gene expression in cells infected in ADE compared to conventional infection conditions, select immune signaling molecules were enriched, including top upregulated DEGs CCR7, ISG15, IL23A, and TRAF." (PMID 39902963, 2025). "Interestingly, BMDMs challenged with GRA15-deficient tachyzoites (PRUΔgra15) consistently exhibited a significantly decreased Ccr7 expression, compared with wild-type-challenged BMDMs at similar infection frequencies." (PMID 39207098, 2024). "However, Ccr2/Ccr7 double knockouts eliminate iMO recruitment following infection with either virus, indicating these receptors together control iMO recruitment." (PMID 38658802, 2024). "Notably, FcεR1γ-deficient ILC3s showed a significant decrease in the expression of infection-induced immune activation genes, such as Fcgr3, Ccr7, Il22, Il17a and Cd93." (PMID 39013884, 2024). "This study investigated whether the ssc-miR-320-mediated regulation of CCR7 affects the expression of IFN-β during SVA infection in PK-15 cells." (PMID 36985261, 2023). "Chemokines and their GPCRs, such as CCL21 and CCR7, are not only important mediators of innate and adaptive immune responses in acute inflammation or infection, but also are continuously fine-tuning an immunological homeostasis, balancing immunity and tolerance." (PMID 36904259, 2023). "When examining individual T cell clones, we observed an increase in CD45RA expression and a concomitant decrease in CCR7 protein expression determined by TotalSeq from acute infection to 6 months after infection, thus confirming an enrichment of a TEMRA phenotype also on a single TCR level." (PMID 34875673, 2022). "The chemokine receptor Ccr7 is required for T cell activation in inflammation and infection." (PMID 35757709, 2022). "In the case of other cell populations, our work did identify modifications in B lymphocyte populations in individuals with a previous infection to vaccination, specifically a decrease in the count of B lymphocytes in peripheral blood that express the chemokine receptor CCR7." (PMID 36052060, 2022). "In the absence of any infection, CCR7-/- mice spontaneously develop BALT (Bronchus-Associated Lymphoid Tissue) due to the lack of tolerance by Tregs42." (PMID 36566320, 2022). "Infection led to robust induction of chemokine and interleukin genes, including Il1b, Il6, Ccl2, Ccl3, Ccl4, Ccl7, Cxcl1, Cxcl2, Cxcl5, Cxcl9, and Cxcl10, and related receptor genes, including Ccr1, Ccr4, Ccr5, Ccr5, Ccr7, Cxcr2, Cxcr5, Il1r2, and Il1rn." (PMID 35487885, 2022). "Similar to our observations of unaltered DC migration to lymph nodes, other infection studies have also observed that DC migration to the lymph nodes was not affected by the lack of β2 integrin, and it is believed that this process is CCR7 dependent." (PMID 33407124, 2021). "Following the infection of hDCs by isolates obtained from patients with different clinical forms of Leishmania, the formation of adhesion complexes, actin polymerization, and CCR7 expression were evaluated." (PMID 34207943, 2021).
infection (continued). "In the context of gut infection, early recruitment of DC to the site of infection is driven by epithelial production of chemokines such as CCL5 whereas DC migration to the lymph nodes is CCR7- dependant, but the role of β2 integrin in this migration is not well characterized." (PMID 33407124, 2021). "In addition, our study showed that transcript abundance of cd4 (Th1 response), cd209 (innate immune response), ccr7 (Th2), and il1b (inflammation) were suppressed during the infection with sea lice alone." (PMID 35046944, 2021). "Additionally, compared to SIVmac239-specific CTLs, greater proportions of RhCMV-specific CTLs were of the terminally differentiated effector memory phenotype (CD28– CCR7–) during chronic SIVmac239 infection." (PMID 32922404, 2020). "This indicates that optimal protective immunity requires CCR7-dependent cell recruitment, which might be of particular importance in infection with more virulent strains such as HN878." (PMID 32198367, 2020). "In addition to, the proportion of all cDCs and of CD11b+ cDCs that were CCR7+ on day 1 after infection in the MLN was also reduced." (PMID 30412605, 2018). "Indeed, HCMV impairs mDC transwell migration capability following a CCL19-chemokine gradient, despite equivalent expression levels of the cognate chemokine receptor CCR7 at the corresponding time points post-infection." (PMID 28484459, 2017). "Our data shows that this process may be supported by infection-induced depression of dendritic-cell expressed CCR7 and reduced migration towards CCL21-dependent gradients." (PMID 26515292, 2015). "Moreover, in experimental murine R. conorii infection increased expression of CCL19 and CCR7 and in particular, CCL21 was associated with lethal infection." (PMID 24507453, 2014). "After infection the frequency of CCR7+ cells increased markedly (p = <0.0001)." (PMID 23326405, 2013). "When B6.CCR7-/- mice were reinfected in the contralateral footpad after 174 days, they first appeared to clear the infection similar to B6.WT mice, according to lesion size, indicating no major impact of CCR7 deficiency on memory formation." (PMID 24205367, 2013). "We concluded that while B6.CCR7-/- mice may be able to control parasite dissemination at an early stage of infection, there is a breakdown of the control, which allows parasites to replicate and cause a chronic disease in these mice." (PMID 24205367, 2013). "Finally, in the controlled SIVagmSab infection of RMs, circulating mDCs showed transient but significant increases of both CCR7 and CCR5 expression." (PMID 24098110, 2013). "Additionally, there was some Foxp3 expression by CD8+ cells, which increased significantly at day 42 post infection in B6.CCR7-/- mice." (PMID 24205367, 2013). "Furthermore, B6.CCR7-/- mice had a greater percentage of cells producing IL-12 at days 14 and 28 post infection than B6.WT mice and most of this production was by cells other than T cells." (PMID 24205367, 2013). "However, infection of B6.CCR7-/- mice with the parasite Toxoplasma gondii, which requires a CD4+ Th1 response, results in death during the acute phase of the disease due to uncontrolled parasite replication and dissemination." (PMID 24205367, 2013). "Furthermore, at days 28 and 42 post infection, B6.CCR7-/- mice have a higher percentage of cells expressing IL-4, which was also seen in the CD4+ compartment but not by CD8+ T cells." (PMID 24205367, 2013). "While parasites could only be found in neutrophils in B6.WT mice after 24 hours post infection, other cells had taken up parasites in B6.CCR7-/- lymph nodes." (PMID 24205367, 2013). "A reduced frequency of lung CD11c+ cells expressing CCR7 was detected in B. pertussis-infected mice compared to cells derived from B. parapertussis and BpΔPTX infections, which were 0.53, 0.80, and 0.76- fold, respectively, over corresponding cells in uninfected mice (p<0.05)." (PMID 23300813, 2012).
infection (continued). "Thus, careful dissection of the roles of CCR7 signaling in different models of CNS immune responses will be useful in understanding leukocyte trafficking during autoimmune responses or infection." (PMID 22533989, 2012). "We then analyzed whether lung DCs from the infection models differ in their potential capabilities to enter the lung draining lymph nodes, as analyzed by the frequency of CD11c+ cells that express CCR7 and CXCR4." (PMID 23300813, 2012). "The expression levels of CCR7 mRNA were quantified 24 h post-infection." (PMID 21731495, 2011). "In contrast with CD8+ T cells, CD4+ T cells show a primarily central memory effector (CCR7+ CD45RA−) phenotype eight months after infection which, with self-renewing capacity, indicates that SARS-CoV-2 specific T cell memory after infection might be long lasting and maintained for many years." (PMID 38027416, 2023). "However, there are likely other contributors to parasite dissemination in the malnourished mice since we observed that splenic infection was not completely abrogated when CCR7-deficient monocytes were transferred to the dermal site of infection." (PMID 36630476, 2023). "Interestingly, CCR7, which can mediate IL-23 production in murine DCs30 followed a similar expression pattern, with higher levels in female compared to male lungs in late stage infection." (PMID 32198367, 2020). "The higher susceptibility of the CCR7- Tm cells to HIV infection is consistent with the notion that Tem (which are CCR7-) are preferentially targeted for infection and may be attributable to the relatively higher levels of CCR5 on these cells relative to their CCR7+ counterparts." (PMID 32452381, 2020). "CCR7 expression on porcine peripheral iNKT cells could therefore also explain the significant in vivo increases of iNKT cell frequencies in regional lymph nodes during infection with IAV (H1N1) as well as with ASFV strain Armenia08." (PMID 31316500, 2019). "Indeed in CCR7-deficient mice, BALTs developed spontaneously in the absence of infection, an event that is directly reverted by the adoptive transfer of wild-type Tregs but not CCR7−/− Tregs." (PMID 27752258, 2016). "However, it is unknown if these monocytes have recently been recruited to the site of infection, or if they have upregulated CCR7 in preparation for migration to the draining lymph node." (PMID 24205367, 2013). "Thus, the changes in CCR7 expression that we observed may be transient and limited to the acute phase of infection." (PMID 23326405, 2013). "Interestingly, a previous study in rhesus macaques reported a loss of CCR7-expressing but not CD62L-expressing CD56+ NK cells after SIV-infection." (PMID 23028633, 2012). "However, during the acute phase of infection with the protozoan parasite, Toxoplasma gondii, CCR7 appeared to be an absolute requirement for the generation of protective immune responses, despite the systemic nature of this infection and the presence of abundant antigen." (PMID 22533989, 2012). "Our data now suggest that these cells may have a beneficial function in vivo, as lymph node mDC with significantly lower expression of CCR7 and costimulatory molecules consistent with a semimature state were present only in animals with long-term stable infection." (PMID 21203477, 2010). "The up-regulation of CCR7 and down-regulation of CD163 explain the enhanced immune activation and reduced anti-inflammatory effects, contributing to more effective infection control." (PMID 41586186, 2025). "For example, TYROBP, CCR7, CXCL10, and CXCL11 emerged as top DEGs in both infected and bystander cells in ADE compared to conventional infection." (PMID 39902963, 2025). "EBV-specific immune cells differentiated into memory CD4+ (including CD45RA−CD45RO+CCR7− effector memory [EM] and CD45RA−CD45RO+CCR7+ central memory [CM] ~ 0.1%) and CD8+ (2–5%) T cells after infection." (PMID 38280072, 2024).
infection (continued). "This suggests that the combined effect of infection and PGE2 on CCR7 expression in this model is relatively selective for monocytes." (PMID 36630476, 2023). "Infection of inflammatory monocytes with L. donovani induced PGE2 production and upregulated CCR7 expression, which was blocked by inhibition of PGE2 synthesis." (PMID 36630476, 2023). "Collectively, these data show that CCR7-bearing infected inflammatory monocytes accumulate in the spleen after intradermal infection of malnourished mice with L. donovani, and that PGE2 regulates CCR7 expression and trafficking of infected monocytes." (PMID 36630476, 2023). "After transfecting iNC/si-CCR7/plasmid NC/plasmid CCR7 into PK-15 cells, the cells were infected with SVA at a 1 MOI and harvested 24 h post-infection." (PMID 36985261, 2023). "To determine the changes of CD4+ and CD8+ T-cell subset composition among PLWH during breakthrough infection, we used flow cytometry to analyze T-cell subsets according to the expression of CD45RA, CD27, and CCR7." (PMID 38140668, 2023). "To further investigate the role of glycolysis in the effector function of CD1c+ mDCs in response to infection with BCG, we analyzed the cell surface expression levels of the costimulatory molecule CD40 and the chemokine receptor CCR7." (PMID 37475964, 2023). "Equally pivotal is data showing that despite CD4 T cell depletion during infection, frequencies of CCR5 and CCR7 within the CNS remain relatively stable." (PMID 38060615, 2023). "B cell transcriptomics indicated significant downregulation of several adhesion molecules during infection, including S1PR1, S1PR2, ITGA4, ITGA6, GPR183, and CCR7." (PMID 37146079, 2023). "This study investigated the regulatory relationship between ssc-miR-320, CCR7, and IFN-β during SVA infection in PK-15 cells." (PMID 36985261, 2023). "Our results show that both UL40-sepcific and pp65-specific responses belong to TEMRA cells after a primary infection and display a stable CD27-/CD28-, CCR7-, CD45RA+, CD8+ TEMRA phenotype which persist lifelong in HCMV+ healthy hosts." (PMID 36532017, 2022). "Since CCL19 and CCL21 are the unique ligands for CCR7, contributing to DC migration into the dLN, we treated mice with CCL19- and CCL21-neutralizing Abs prior to infection and subsequently measured bacterial burdens in dLN." (PMID 36618364, 2022). "We observed increased numbers of CCR7+ and CD62L+ CD4+ T cells in anti-CD300a antibodies treated mice, which was significant at the later stages of infection (D14 and D21)." (PMID 35116028, 2021). "To characterize the state of differentiation of CAR-transduced T lymphocytes in the post-infection period and during antigenic restimulation, we cytometrically analyzed the expression of different surface markers, namely CD62L, CD27, CD28, CCR7, and CD57." (PMID 34660275, 2021). "We also FACS-sorted the different CD4TL subsets with anti-CCR7 and CD45RA mAbs and then subjected them to single-cycle infection with SENS viruses, RES viruses, JR-FL or NL4-3." (PMID 33872329, 2021). "Our results show that infection by L. infantum, Lb DL and La DCL isolates induces CCR7 expression in hDCs, suggesting the participation of this molecule with parasite dissemination in the vertebrate host." (PMID 34207943, 2021). "In one hand, several mouse models revealed that deficiency of CCR7 signaling was not a life-threatening condition, as it was associated with a moderate impact on immunity by retarded, but preserved, T-cell and B-cell responses, especially against infections with replicating antigens." (PMID 34778050, 2021). "Most of the genes for chemokines/chemokine receptors (CCR2, CCR6, CCR7, CSF2RB, CX3CR1 and CXCR4) and cytokines/cytokines receptors (IL1R2, IL8, IL18, IL20RA and IL22RA2) were down-regulated after infection by vvIBDV at 3 dpi." (PMID 33110122, 2020).